ADA (adenosine deaminase)
Diseases named in the same sentence as ADA in open-access papers (continued):
Sharing a sentence is not in itself a finding about the gene and the disease.
Cryptococcal meningitis (4 papers, 2016 to 2022). Meningeal inflammation produced by cryptococcus neoformans, an encapsulated yeast that tends to infect individuals with acquired immunodeficiency syndrome and other immunocompromised states. "In conclusion, we report an older patient with cryptococcal meningitis associated with increased CSF ADA level, in which information on the chronological change in CSF ADA level was useful for follow-up assessment." (PMID 28028491, 2016). "We report of an older patient with cryptococcal meningitis associated with increased CSF ADA level, in which information on the chronological change in ADA level was useful for follow-up assessment." (PMID 28028491, 2016). "ADA can also be found in patients infected with HIV or who have other HIV-associated neurological diseases, such as cryptococcal meningitis, lymphomatous meningitis, and cytomegalovirus disease." (PMID 36362480, 2022). "A statistically significant difference was found when comparing CSF ADA results between the ‘Confirmed cryptococcal meningitis’ and ‘Confirmed TBM’ categories." (PMID 28143441, 2017). "We report a case of a 67-year-old woman with cryptococcal meningitis presented with increased ADA level of the CSF." (PMID 28028491, 2016). "Cryptococcal meningitis should be considered for the differential diagnosis for diseases presented increased CSF ADA." (PMID 28028491, 2016). "This is the first case described the chronological change in CSF ADA level of the patient with cryptococcal meningitis in detail." (PMID 28028491, 2016). "From the detailed observation of CSF ADA level, the determination of CSF ADA level was useful for follow-up assessment of cryptococcal meningitis." (PMID 28028491, 2016). "Because there was not the chronological change of CSF ADA level in previous reports, it was not clear whether increased CSF ADA level was caused by cryptococcal meningitis." (PMID 28028491, 2016). "In addition, other promising sensitive and specific targets, such as immunoglobulin and adenosine deaminase levels, may be useful adjunctive tests for the differential diagnosis of tubercular/cryptococcal meningitis, and these tests need to be evaluated in further studies." (PMID 28831193, 2017). "Although the determination of CSF ADA level can be useful for early differential diagnosis of TBM, other neurological diseases such as cryptococcal meningitis should be considered." (PMID 28028491, 2016). "We describe an older woman with increased CSF ADA level, who was diagnosed with cryptococcal meningitis rather than TBM." (PMID 28028491, 2016).
diabetic nephropathy (4 papers, 2021 to 2025). "Indeed, the use of adenosine deaminase, which decreases adenosine by converting it to inosine, has been shown to prevent α-SMA induction in experimental diabetic nephropathy." (PMID 40558517, 2025).
diabetic retinopathy (4 papers, 2013 to 2022). "In experimental diabetic retinopathy (DR), ADA promotes the progression of DR by participating in the destruction of the blood-retinal barrier (BRB) through macrophage-derived cytokines, and inhibition of ADA can preserve BRB function." (PMID 34319903, 2021).
dyslipidemia (4 papers, 2014 to 2026). "However, ADA activity decrease under pre‐training conditions in platelets and lymphocytes of metabolic syndrome patients." (PMID 36117383, 2022).
encephalitis (4 papers, 2006 to 2025). An acute inflammatory process affecting the brain parenchyma. "CSF ADA levels in a previous study containing data on 10 patients with viral encephalitis were found to have a mean (SD) of 6.15 (2.93), which is higher than the levels reported here (3.8 (1.0) IU/l)." (PMID 16764711, 2006). "We found that a CSF/serum ADA ratio of <0.38 was the best discriminator of cerebral malaria from presumed viral encephalitis." (PMID 16764711, 2006). "Specificities for the parameters were 100% for CSF glucose and 100% for CSF/serum ADA ratio and better than for other parameters, i.e. presumed viral encephalitis was always present in any patient with a value above the cut-off." (PMID 16764711, 2006). "Patients with cerebral malaria had significantly lower CSF glucose, protein and LDH levels and CSF/serum ADA ratios compared to patients with presumed viral encephalitis." (PMID 16764711, 2006). "CSF/serum ADA ratio and CSF glucose levels were the best discriminators of cerebral malaria from presumed viral encephalitis in our study." (PMID 16764711, 2006). "Patients with cerebral malaria had a significantly higher serum ADA level compared to patients with presumed viral encephalitis and to controls (Mann-Whitney test, p < 0.05)." (PMID 16764711, 2006). "Patients with cerebral malaria had lower CSF white cell count, glucose, protein, LDH levels and CSF/serum ADA ratio compared to patients with presumed viral encephalitis." (PMID 16764711, 2006). "CSF adenosine deaminase alone was not a useful discriminator between encephalitis and cerebral malaria." (PMID 16764711, 2006). "Serum ADA levels in patients with presumed viral encephalitis were not significantly different from controls (p > 0.05)." (PMID 16764711, 2006).
gastric cancer (4 papers, 2013 to 2024). A primary or metastatic malignant neoplasm involving the stomach. "Given that the higher ADA activity in cancer tissue might underlie the decreased adenosine concentration, higher escape from apoptosis might be occurring in gastric cancer because of low extracellular adenosine levels." (PMID 29018360, 2017). "Although no studies have yet reported on COL10A1, ADA, or LHFP and cancer survival, CTSB and MMP9 have both been previously associated with survival in gastric cancer, while ESRRG expression has been associated with survival in prostate cancer." (PMID 23717493, 2013).
hairy cell leukaemia (4 papers, 2018 to 2024). "So far, 2′deoxycoformycin is the only adenosine deaminase inhibitor in clinical use that currently is limited to the treatment of adult patients with hairy cell leukemia." (PMID 33053898, 2020). "Pentostatin, a purine analogue inhibiting adenosine deaminase (ADA), is used against hairy cell leukaemia; ADA amplification is a resistance mechanism in vitro." (PMID 30041457, 2018). "Pentostatin is a potent inhibitor of adenosine deaminase (ADA), which was approved by the FDA in 1991 and became a commercial drug for the treatment of hairy cell leukemia (under the brand name Nipent)." (PMID 39199741, 2024).
head and neck cancer (4 papers, 2014 to 2025). A primary or metastatic malignant neoplasm affecting the head and neck. "This test has been successfully employed to diagnose adenosine deaminase 2 deficiency (DADA2) and potentially to identify individuals with head and neck cancer." (PMID 40936927, 2025). "Few studies have evaluated the presence of CD26 or the direct activity of ADA in MSCs, such as those from head and neck cancer, BM, UCB, and adipose tissue." (PMID 39273524, 2024). "Some authors have reported significantly increased serum levels of ADA in patients with head and neck cancer, thus suggesting that serum ADA may be useful for the diagnosis and follow-up of the disease." (PMID 37958429, 2023).
Hyperglycemia (4 papers, 2013 to 2026). An increased concentration of glucose in the blood. "DKD is a multifactorial disease, and disordered glucose and lipid metabolism and alterations in hemodynamics, inflammation and oxidative stress are all involved in its onset and progression, while serum ADA levels are closely associated with hyperglycemia, inflammation, and hypercoagulability." (PMID 34319903, 2021). "Interestingly, depending on the duration of the hyperglycaemia, ADA altered UKV in the opposite direction: an increase or a decrease was seen in DM-14 and DM-60 animals, respectively." (PMID 37242515, 2023). "The effects on the renal haemodynamics and excretion of ADA, an enzyme that reduces the level of adenosine (endogenous agonist of A1, A2, and A3 receptors) and the effects of A2aR selective antagonist, were determined in anaesthetised NG and DM rats with short- or long-lasting hyperglycaemia." (PMID 37242515, 2023). "Thus, high serum ADA levels in patients with T2D may partly reflect the degree of hyperglycemia, inflammation, and hypercoagulability." (PMID 34319903, 2021).
leishmaniasis (4 papers, 2015 to 2024). Infectious disease that is transmitted through the bite of hematophagous female phlebotomine sand flies. "In our opinion, it is prudent to use rK39 strip and ADA in tandem, because seropositivty for rK39 and elevated serum ADA always associated with clinical leishmaniasis." (PMID 27186641, 2016). "Deamination of salivary nucleosides with ADA—an enzyme that catabolizes ADO—markedly abolished the exacerbative effects of SGEs during leishmaniasis." (PMID 25849562, 2015). "Adenosine deaminase is an enzyme involved in the catabolism of purine bases and its main physiologic activity is related to lymphocytic proliferation and differentiation, suggesting an important role for immune responses and consequently as a potential target for leishmaniasis vaccine development." (PMID 38633260, 2024). "In leishmaniasis, there are increased levels of proinflammatory mediators including TNF-α, CRP and adenosine deaminase." (PMID 39539349, 2024).
Nijmegen breakage syndrome (4 papers, 2013 to 2025). Nijmegen breakage syndrome is a rare genetic disease presenting at birth with microcephaly, dysmorphic facial features, becoming more noticeable with age, growth delay, and later-onset complications such as malignancies and infections. "The combined TREC/KREC assay has some advantages such as the identification of patients with late-onset ADA, X-linked agammaglobulinemia, autosomal recessive agammaglobulinemia or cases of Nijmegen breakage syndrome." (PMID 39982345, 2025).
Opportunistic infection (4 papers, 2018 to 2021). An infection that is caused by a pathogen that would generally not be able to cause an infection in a host with a normal immune system. "It is believed that ADA-SCID patients, owing to immune system abruption, are more likely to develop aHUS as a result of disease caused by a wider range of pathogens, or even an opportunistic infection." (PMID 34502390, 2021).
Parkinson disease (4 papers, 2009 to 2021). A progressive degenerative disorder of the central nervous system characterized by loss of dopamine producing neurons in the substantia nigra and the presence of Lewy bodies in the substantia nigra and locus coeruleus. "Suppression of ADA resulted in beneficial effects in a MPTP-induced Parkinsonism mouse model but toxic effects on motor neurons in an ALS model established with a cocultured system of induced pluripotent stem cell (iPSC)-derived astrocytes and motor neurons." (PMID 34635103, 2021).
pulmonary alveolar proteinosis (4 papers, 2016 to 2023). A rare lung disorder characterized by the filling of the pulmonary alveoli with proteinaceous material which stains positive with periodic acid-Schiff stain. "This assumption is corroborated by reports from ADA-deficient patients: These studies demonstrate that ADA-deficient patients develop renal complications (sclerosis) as well as pulmonary complications (pneumonitis, pulmonary alveolar proteinosis, fibrosis)." (PMID 31623231, 2019). "Another pulmonary phenotype observed in ADA-deficient mice is pulmonary alveolar proteinosis (PAP), a rare lung disorder that can result in progressive respiratory failure." (PMID 27579027, 2016).
respiratory infection (4 papers, 2021 to 2023). "Of those with a normal ALT level, significantly more children with IM (97.3%) and atypical EBV infection (91.7%) had an elevated ADA level than those with a respiratory infection (45.8%), malignant disease (57.1%), or other diseases (51.4%) (P < 0.05)." (PMID 35986367, 2022). "Finally, patients with IM, atypical EBV infection, and respiratory infection in the elevated ALT level group had higher ADA levels than those in the normal ALT level group." (PMID 35986367, 2022). "In contrast, only half of the children with EBV-related respiratory infections and malignant diseases had an elevated ADA level, likely because EBV infection may not be the primary cause of the disease or the EBV infection did not elicit a strong immune response." (PMID 35986367, 2022). "None of the patients had infections prior to transplant, with the exception of P11, a patient with ADA-SCID (sibling of P10) who had two observational hospitalizations for rhino/enterovirus and parainfluenza upper respiratory infection, neither of which required any respiratory support." (PMID 34539671, 2021).
schizophrenia (4 papers, 2019 to 2025). A major psychotic disorder characterized by abnormalities in the perception or expression of reality. "In the Brassilian cohort of schizophrenia patients study, which examined schizophrenia patients, low ADA enzyme activity was associated with a low-activity adenosine deaminase allelic variant." (PMID 40439810, 2025). "After that, the predictive value of the schizophrenia risk model for serum ADA Level was determined using a binary logistic regression analysis." (PMID 40439810, 2025). "The results showed that serum ADA levels were significantly different between individuals at relatively low genetic risk (healthy controls) for schizophrenia and those at relatively high genetic risk (patients and relatives)." (PMID 40439810, 2025). "Evaluation with serum ADA level is highly sensitive and can guide the clinician in distinguishing the low-risk group from the high-risk group in terms of schizophrenia." (PMID 40439810, 2025). "Because all of the patients and their families had a genetic predisposition to schizophrenia and had significantly lower ADA levels than the control group, they were combined into a single group." (PMID 40439810, 2025). "This study aimed to examine the possible correlation between high-risk psychosis and ADA levels, which have been linked to schizophrenia in previous studies." (PMID 40439810, 2025). "A rare polymorphism of ADA with lower enzymatic activity was found to be less frequent in a Brazilian cohort of schizophrenia patients." (PMID 36998267, 2023). "If possible, we assert that serum ADA measurement could be a relatively inexpensive and accessible method to assist clinicians in estimating schizophrenia risk." (PMID 40439810, 2025). "Hence, there are some grounds to suspect an association of elevated ADA activity with schizophrenia in the direction as predicted by the adenosine hypofunction hypothesis." (PMID 36998267, 2023). "The general consensus in the literature is that ADA enzyme levels are higher in schizophrenia patients than in healthy populations." (PMID 40439810, 2025). "In this cross-sectional case–control study, the serum levels of adenosine deaminase were compared among patients with schizophrenia, first-degree relatives of schizophrenia patients, and healthy controls." (PMID 40439810, 2025). "The results of our study, which demonstrate reduced levels of ADA enzyme in individuals with schizophrenia, contrast with those reported in previous studies." (PMID 40439810, 2025). "The same study that reported reduced ENT1 mRNA in DLPFC pyramidal neurons in schizophrenia found increased levels of the irreversible enzyme ADA, suggesting lower levels of adenosine in schizophrenia compared to control subjects." (PMID 38201235, 2023). "Evidence of increased ADA activity in schizophrenia patients treated with antipsychotic drugs has been obtained by measuring the enzymatic activity of serum ADA." (PMID 36998267, 2023). "Increased ADA gene expression levels have been detected in pyramidal neurons of the DLPFC of schizophrenia patients compared with controls." (PMID 36998267, 2023). "ADA is a peripheral biomarker of schizophrenia correlating with the antipsychotic efficacy of clozapine and involved in the purine metabolism pathway." (PMID 31477693, 2019). "Studies on the relationship between the adenosinergic system and schizophrenia have been released, but none has explored the relationship between adenosine deaminase and psychosis risk." (PMID 40439810, 2025). "These authors went on to suggest using elevated serum ADA levels as a biomarker of schizophrenia." (PMID 36998267, 2023). "In addition, a systematic evaluation of the effects of antipsychotic drugs on the expression of ADA, EctoNT, and ENT may help separate possible adenosinergic disturbances intrinsic to schizophrenia from those that may be caused by antipsychotic mediation." (PMID 36998267, 2023).
X-linked agammaglobulinemia (4 papers, 2020 to 2025). X-linked agammaglobulinemia (XLA) is a clinically variable form of isolated agammaglobulinemia, an inherited immunodeficiency disorder (see this term), and is characterized in affected males by recurrent bacterial infections during infancy. "Wiskott–Aldrich syndrome (WAS), X-Linked agammaglobulinemia (XLA), and adenosine deaminase (ADA) deficiency are inborn errors of immunity (IEI), a group of over 485 genetic disorders that compromise immunity due to an improperly functioning immune system." (PMID 39846592, 2025).
Aicardi-Goutières syndrome (3 papers, 2020 to 2025). "Here, we studied the biological function(s) of Z-RNA recognition by the adenosine deaminase ADAR1, mutations in which cause Aicardi-Goutières syndrome." (PMID 34525337, 2021).
anaphylaxis (3 papers, 2025). An acute hypersensitivity reaction that occurs from exposure to an allergen. "It is noteworthy that none of our patients experienced anaphylaxis, in contrast to the ASCEND-PED study, which reported a case of anaphylaxis associated with anti-drug antibodies (ADA+) that required desensitization." (PMID 40810828, 2025). "Patients without anaphylaxis or SAEs and those with fewer HAEs throughout the PRISM-1 induction and titration phases generally had lower ADA titers and greater pegvaliase Ctrough." (PMID 40542371, 2025).
Artemis deficiency (3 papers, 2022 to 2025). "It is worth mentioning that according to the literature, P1 seems to be the third case of ADA deficiency and P2 the fourth case of Artemis deficiency reported in the Greek population." (PMID 41011036, 2025). "Sixpatients had ADA deficiency, 3 had IL2RG deficiency, 3 had CD3 Delta deficiency, 2 had Artemis deficiency (affecting DCLRE1C), and 1 each had variants impacting NHEJ1, TRAC, RAC2, and RMRP." (PMID 39062699, 2024). "from 2020 more than 30 gene therapy clinical trials on monogenic diseases (phase I to phase III) were registered, including X -linked SCID (X1-SCID) (ILR2G), ADA-SCID (ADA), Wiskott- Aldrich (WAS), X-CGD (CYBB), Leukocyte adhesion deficiency (CD18) and Artemis-deficiency (ART) SCID (DCLRE1C)." (PMID 36569887, 2022).